HLA-G (major histocompatibility complex, class I, G)
Diseases named in the same sentence as HLA-G in open-access papers (continued):
Sharing a sentence is not in itself a finding about the gene and the disease.
breast carcinoma (continued). "In plasma samples from patients with ER+ breast cancer before receiving NACT, they observed a significant correlation between exosome-derived soluble HLA-G levels, tumour progression and overall survival, but not for pCR42." (PMID 32978482, 2020). "Inhibition of HLA-G or PDL1 did however not alleviate the suppressive effect that CD169+ Mo-M had on T cells, nor affect NK cell cytotoxicity in co-cultures with macrophages and breast cancer cells." (PMID 37404831, 2023). "For both breast cancer cell lines, IFN-γ treatment did not have an effect on HLA-G mRNA levels." (PMID 32560316, 2020). "A comprehensive study by Polakova and Russ on 75 different cancer cell lines including melanoma and breast cancer (e.g., MDA-MB-231 and MCF-7) imply that under normal culture conditions the cell surface expression of HLA-G is absent in most cancer cell lines across different origin." (PMID 32560316, 2020).
melanoma (64 papers, 2008 to 2025). A malignant, usually aggressive tumor composed of atypical, neoplastic melanocytes. "Elevated expression of HLA-G has been reported in various cancers, including melanoma and myeloma, and is associated with poor prognosis." (PMID 39741180, 2025). "We have recently shown an association between high HLA-G expression and a high frequency of FoxP3+ tumor-infiltrating lymphocytes in malignant melanoma patients." (PMID 31134056, 2019). "This study indicated that HLA-G expression can enable classic HLA I deficient melanoma cells to lose responsiveness to IFN-α treatment." (PMID 30319626, 2018). "Several malignancies since then have associated HLA-G expression with outcome including lung cancer, melanoma, renal cancer, colon cancer, cervical cancer, endometrial carcinoma, oesophageal cancer, glioblastoma, gastric cancer, and breast cancer, among others." (PMID 39766165, 2024). "Furthermore, as described in melanoma cell lines, expression of HLA-G can account for susceptibility to NK-mediated lysis due to a switch in alternative splicing." (PMID 24987709, 2014). "Lastly, further studies are needed to improve the comprehension of LEVs and HLA-G roles in oncological contexts, especially in different melanoma subtypes." (PMID 41268555, 2025). "Since HLA-G expression was first observed in melanoma, over the last three decades, its expression has been explored in more than 30 types of pathological cancers, including CRC." (PMID 41194925, 2025). "It has been shown that NK cells can acquire HLA-G from HLA-G+ tumor cells, leading to impaired cytotoxicity against HLA-G- melanoma targets." (PMID 41445738, 2025). "Similar to T cells, NK cells can acquire the immune regulatory protein HLA-G from the HLA-G1-transfected melanoma cell line M8-HLA-G1 via trogocytosis." (PMID 39741180, 2025). "We also observed a higher count of LEVs-HLA-G+ in males than females from the melanoma group (3.15E + 04 ± 2.86E+04 vs. 1.64E + 04 ± 1.14E+04, p=0.05), which was less evident for sHLA-G (5.52 ± 4.88 vs. 3.15 ± 2.55ng/mL, p=0.08)." (PMID 41268555, 2025). "Nevertheless, LEVs-HLA-G+ seems to be related to melanoma subtypes, especially with acral lentiginous melanoma." (PMID 41268555, 2025). "Overexpression of HLA-G was first found in melanoma samples with an absence in adjacent healthy tissues." (PMID 39766165, 2024). "We select this melanoma cell line since it was in this cell line that was demonstrated for the first time the role of HLA-G in tumor progression." (PMID 39358558, 2024). "Aberrant HLA-G expression in cancers was first reported in 1998 in melanoma cells, and since then, HLA-G has been evaluated worldwide in malignant samples of various cancer types." (PMID 38391781, 2024). "Functional analysis of control (shCtrl) and HLA-G depleted (shHLA-G1 and 2) parental lung and melanoma BMICs in vitro revealed a reduction in the secondary sphere formation abilities of lung and melanoma BMICs upon HLA-G knockdown." (PMID 36780531, 2023). "We also observed reduced SPAG9 expression in HLA-G-depleted lung and melanoma BMICs, indicating a positive correlative relationship between HLA-G and SPAG9 in BMICs." (PMID 36780531, 2023). "Immunoprecipitation studies confirmed the association of HLA-G with SPAG9 in lung and melanoma BMICs." (PMID 36780531, 2023). "We also observed a reduction in the proliferation of lung and melanoma BMICs upon HLA-G knockdown 4-d postseeding, indicating a role for HLA-G in tumor cell proliferation that has also been reported elsewhere." (PMID 36780531, 2023). "We also observed increased p-STAT3 levels in melanoma BMICs upon HLA-G overexpression, signifying that HLA-G activation of STAT3 signaling is not restricted only to lung BMICs." (PMID 36780531, 2023). "Intriguingly, suppression of STAT3 signaling with DR-1-55 in HLA-G OE BMICs caused a drastic decline in the secondary sphere formation of HLA-G OE lung and melanoma BMICs despite the presence of high HLA-G levels in these cells." (PMID 36780531, 2023).
melanoma (continued). "Nonetheless, we found that SPAG9 ablation in HLA-G OE lung and melanoma BMICs diminished the expression of p-STAT3 despite the high HLA-G levels present in these cells, demonstrating that HLA-G modulates STAT3 signaling in BMICs via SPAG9." (PMID 36780531, 2023). "Surprisingly, we noticed an increase in SPAG9 protein levels in HLA-G OE lung and melanoma BMICs compared to their respective controls." (PMID 36780531, 2023). "HLA-G expression in tumor lesions was first demonstrated in melanoma and later, its expression has been correlated with poor clinical outcomes in various cancer patients." (PMID 35626255, 2022). "Activation of HLA-G expression by IL-10 is indicated in melanoma cells, thereby contributing to the tumor escape from immunosurveillance." (PMID 36437782, 2022). "For the malignant melanoma cell lines, we also performed the analysis on unstimulated control cells, since ddPCR showed low levels of HLA-G mRNA before treatment." (PMID 32560316, 2020). "HLA-G-expressing DCs have been detected in many types of tumor in vivo, such as in lung, breast, and ovarian cancer and melanoma, and correlated with a poor clinical outcome." (PMID 33425752, 2020). "The expression of HLA-G in melanoma has been studied and demonstrated to be increased compared to melanocytic nevi, correlating HLA-G expression with cell transformation." (PMID 32922387, 2020). "HLA-G expression was also demonstrated to be increased on inflammatory infiltrating cells within the melanomas compared to nevus." (PMID 32922387, 2020). "What brings another level of complexity in the detection of HLA-G and the understanding of its role in cancer progression is the existence of micro-vesicles bearing HLA-G, firstly described in the supernatant of HLA-G positive melanoma cells in vitro." (PMID 32922387, 2020). "Similar results have been observed for the melanoma cell line OCM-1A where bisulfite sequencing revealed methylation of 87% of CpG sites in the promoter region of HLA-G before treatment compared to only 2% after treatment." (PMID 32560316, 2020). "We have previously shown an association between high HLA-G and HLA-ABC expression with tumor aggressiveness and a worse prognosis in a study including 250 malignant melanoma patients." (PMID 32560316, 2020). "Other groups demonstrated in vitro the immune-tolerogenic properties of HLA-G, protecting melanoma cell lines from the NK cells cytotoxicity, which were confirmed in vivo on xenogeneic melanoma models." (PMID 32922387, 2020). "With some variations in the data, there was a strong tendency towards induction of HLA-G mRNA upon treatment with 5-aza-dC in both malignant melanoma cell lines." (PMID 32560316, 2020). "The effect of IFN-γ on HLA-G mRNA expression in malignant melanoma cell lines displayed a marked heterogeneity." (PMID 32560316, 2020). "Higher HLA-G expression has been described in other skin disorders, including melanoma, psoriasis, and pemphigus vulgaris." (PMID 31505868, 2019). "HLA-G expression is induced in the melanoma cell line OCM-1A after treatment with 5-aza-2’-deoxycytidine." (PMID 30899759, 2019). "Expression of HLA-G and the presence of FoxP3+ tumor-infiltrating lymphocytes is also believed to contribute to the suppression of effective T cell immune responses in melanoma." (PMID 31134056, 2019). "Local induction of HLA-G in the presence of inflammatory T cell infiltrates has also been reported in melanoma." (PMID 29464090, 2018). "In that study, they found that the status of classic HLA I molecules and HLA-G expression were significantly related to the outcome of melanoma patients receiving IFN-α-2b treatment." (PMID 30319626, 2018). "Seven haplotypes provided higher response in FON+ than in JEG-3 cells, a result that is in line with the higher HLA-G expression observed in the melanoma cells." (PMID 29618829, 2018).
melanoma (continued). "HLA-G-bearing EVs were first observed in culture supernatants of an HLA-G+ melanoma cell line (Fon), and later in ascites and pleural exudates from cancer patients." (PMID 30319626, 2018). "Intriguingly, opposite effects in HLA-G expression in the presence of hypoxia-mimicking treatment were found in HLA-G+ melanoma FON and JEG-3 cells: transcript levels were decreased by an average of 67.8% and 38.5% in FON and JEG-3 cells, respectively." (PMID 28781970, 2017). "Chang and Ferrone analyzed HLA-G mRNA levels in melanoma cell lines using as positive internal control the JEG-3 choriocarcinoma cell line that constitutively expresses higher levels of HLA-G (HLA-G+), both at the transcriptional and protein level." (PMID 28781970, 2017). "Among tumors, malignant melanoma was the first type of cancer in which HLA-G transcripts were detected since 1998." (PMID 28781970, 2017). "Previous reports have shown that gamma radiation and/or chemotherapy modulates surface HLA-G expression in B-cell lines (M8 and K562), melanoma cell lines (OCM-1A and JEG-3) and basal cell carcinoma of the skin." (PMID 29285306, 2017). "Particularly, HLA-G can be induced by hypoxia or hypoxia-mimicking conditions with melanoma cell lines cultured in the presence of desferrioxamine (DFX)." (PMID 27577073, 2016). "A high expression of HLA-G and regulatory T cells have both, separately, been shown to worsen the outcome of malignant melanoma." (PMID 27999823, 2016). "Secreted HLA-G-expressing EVs have been detected for the first time in supernatants of a melanoma cell line, originated from a HLA-G-positive melanoma lesion." (PMID 27199995, 2016). "It will be interesting in the future to explore the opportunities for modulating HLA-G expression in melanoma tumor cells and other tumors or induce an HLA-G peptide-specific immune response as new innovative cancer immunotherapy." (PMID 27999823, 2016). "In general, HLA-G transcription is induced by heat shock (physical stress) or arsenate treatment (chemical stress) in human melanoma and glioblastoma cell lines, in which stress-induced HSF1 binds to an HSE lying between the −464 and −453 positions." (PMID 24741620, 2014). "Studies of the methylation levels of 450 bp of the promoter region of HLA-G in melanoma and choriocarcinoma cell lines showed a correlation between expression and low levels of methylation." (PMID 18498645, 2008). "In accordance, glioma cell lines expressing HLA-G are resistant to allo-reactive lysis, and HLA-G-positive melanoma cell lines are protected from NK cell cytolysis." (PMID 18397301, 2008). "A significant difference between IL-6 supernatant concentrations was observed between the control leukocyte and those stimulated with recombinant HLA-G at 100ng (p<0.001) and the control leukocyte and those stimulated with LEVs from melanoma patients in a proportion 1:10 (p=0.01)." (PMID 41268555, 2025). "In melanoma, HLA-G seems to reflect tumor aggressiveness and could be an important biomarker in these cases." (PMID 41268555, 2025). "Although the relationship between HLA-G and IL-6 is not clear in some cancer types, in melanoma, IL-6 signaling associated with HLA-G expression seems to amplify immunosuppression and cancer evasion." (PMID 41268555, 2025). "A preliminary in vitro assay showed that HLA-G may increase IL-6 secretion by leukocytes in the same way that plasma-derived LEVs from melanoma patients." (PMID 41268555, 2025). "Considering these results, we highlight that melanoma heterogeneity may be an important factor in LEVs and HLA-G release patterns." (PMID 41268555, 2025). "NK cells that received HLA-G from melanoma cells lost their proliferation and tumor-killing capacity and suppressed other NK cells cytotoxicity locally and transiently, while the occurrence of CD3+HLA-Gacq+T cells was significantly correlated with poor prognosis in multiple myeloma." (PMID 38310272, 2024).
melanoma (continued). "Additionally, IFNy causes the upregulation of non-canonical MCH class I molecules such as human leukocyte antigen (HLA)-G and HLA-E50, which limit anti-melanoma cytotoxicity by T cells." (PMID 38167503, 2024). "Additionally, an HLA-G+ cell line (melanoma FON+) transfected with the G010102a haplotype exhibited the lowest promoter activity among all other 5′URR haplotypes when compared to the empty vector." (PMID 37629044, 2023). "However, HLA-G depletion greatly inhibited the capacity of lung and melanoma BMICs to accumulate in the brain." (PMID 36780531, 2023). "Furthermore, HLA-E and HLA-G expression levels are often elevated in the course of typical melanoma immune escape strategies." (PMID 33925968, 2021). "They speculate that the immune tolerance produced by melanoma-derived HLA-G exosomes may be a method for tumors to regulate host immunity." (PMID 34868081, 2021). "To determine whether the effect of HLA-G was cell-dependent, we measure the expression of VEGF-C in the melanoma cell line M8 expressing HLA-G." (PMID 32620162, 2020). "Moreover, the regulation of VEGF-C by HLA-G was shown to be cell-independent since the levels of VEGF-C also increase in a melanoma cell line when transfected with HLA-G." (PMID 32620162, 2020). "Additionally, malignant melanoma cell lines were treated with IFN-γ for four days to test the ability of IFN-γ to induce HLA-G expression after a longer incubation period." (PMID 32560316, 2020). "HLA-G expression has been shown in 22/33 primary tumor tissues of human ovarian carcinoma, but not in normal tissue, and in 30% of surgically removed melanoma lesions." (PMID 30899759, 2019). "In addition, it has been reported that HLA-G expression was present in various cancers (melanoma, breast, colon, lung and renal), and that melanoma cell lines expressing HLA-G isoforms had inhibited cytotoxic responses from NK and T-cells." (PMID 29301290, 2018). "In this context, previous studies showed that HLA-G expression could be induced by 5-aza-2′-deoxycytidine and IFN-γ treatment in vitro in glioblastoma, and an enhanced peripheral sHLA-G level was observed in melanoma patients treated with IFN-α." (PMID 30319626, 2018). "Furthermore, the authors verified the influence of hypoxia on HLA-G expression in different HLA-G− tumorigenic cell lines such as melanoma (M8), choriocarcinoma (JAR), Burkitt's lymphoma (Raji), and glioma (U87MG, LN229, and LN428)." (PMID 28781970, 2017). "A number of studies have investigated HLA-G protein expression in malignant melanoma." (PMID 27999823, 2016). "Therefore, the present work and previous ones, demonstrating that HLA-G gene expression in melanoma cells is induced by hypoxic conditions, clearly support the contribution of this micro-environment factor in the expression and the level of HLA-G expression." (PMID 27577073, 2016). "To date, HLA-G polymorphisms have not been investigated in the context of melanoma, glioblastoma, colorectal cancer, gastric cancer, lung cancer, and renal cell carcinoma." (PMID 25699038, 2015). "Exosomes could act as a mechanism to spread HLA-G tolerogenic functions because HLA-G presence has been demonstrated in exosomes produced by melanoma cells and by early and term placenta." (PMID 24818168, 2014). "Taking it all together we may suggest an interplay between HLA-G and IL-6 in melanoma progression." (PMID 41268555, 2025). "Similarly, melanoma cells were found to express HLA-G as a means of resisting NK-mediated killing." (PMID 41445738, 2025). "Meanwhile, co-culture of HLA-G-expressing melanoma M8 cells with dNK cells could restore the killer cell immunoglobulin-like receptor 2DL4 or immunoglobulin-like transcript 2 expression on dNK cells, which increased the expression levels of surface HLA-G." (PMID 34413856, 2021). "However, HLA-G expressed by melanoma cells was shown to protect them from NK lysis." (PMID 34201301, 2021).